SOCS2 (suppressor of cytokine signaling 2)
Diseases named in the same sentence as SOCS2 in open-access papers (continued):
Sharing a sentence is not in itself a finding about the gene and the disease.
leukemia (14 papers, 2013 to 2026). A malignant (clonal) hematologic disorder, involving hematopoietic stem cells and characterized by the presence of primitive or atypical myeloid or lymphoid cells in the bone marrow and the blood. "SOCS2 has also been implicated in various malignancies, notably including myeloproliferative disorders and leukemias although this can be both pro- and anti- tumorigenic." (PMID 34604264, 2021). "We next sought to determine whether oncogenic RAS leads to reduced SOCS2 expression in fully established human leukemia, where RAS mutations are prevalently detected." (PMID 35352806, 2022). "Next, we further assessed how restoration of SOCS2 expression impacts leukemia cell growth by overexpressing SOCS2 in AML cell lines." (PMID 35352806, 2022). "In this case SOCS2 expression was under the control of the myocyte-specific enhancer factor 2C and was involved in maintaining the stemness of the leukemias." (PMID 34604264, 2021). "For example, PROTACs designed using SOCS2 binders as recruiters would be ideal for degrading targets specifically in cells affected with leukemia and gastrointestinal sarcoma which have been reported to have upregulated SOCS2 expression." (PMID 31182716, 2019). "Importantly, restoration of Socs2 expression significantly mitigated growth of NRAS mutant leukemia cells." (PMID 35352806, 2022). "Instead, oncogenic N-Ras reduces the active enhancer marker H3K27ac at the SOCS2 locus, which may explain the lower gene expression of SOCS2 in NRAS mutant leukemia cells." (PMID 35352806, 2022). "The newly established role of SOCS2 in leukemia aggressiveness and stemness raises the possibility that the signature might even be exploitable therapeutically." (PMID 31235852, 2019). "Another group built a six-gene leukemia stem cell (LSC) score with the incorporation of DNMT3B, GPR56, CD34, SOCS2, SPINK2, and KIAA0125 expressions for pediatric AML." (PMID 33225420, 2021). "The exclusively up-regulated genes in BC cells included SOCS2 and S100A16, which are pivotal in promoting progression of leukemia as well as other types of cancer." (PMID 33226961, 2020). "We demonstrate here that decreased Socs2 level may contribute to enhanced HSC competitiveness and proliferation in the NrasG12D mutant HSPCs, thus facilitating subsequent leukemia development." (PMID 35352806, 2022). "We found that SOCS3, but not SOCS2, was highly expressed in leukemic blood and bone marrow, while leukemia/lymphoma cell lines lacking PCM1-JAK2, including acute eosinophilic leukemia, expressed neither gene." (PMID 23372669, 2013).
gastric cancer (13 papers, 2020 to 2025). A primary or metastatic malignant neoplasm involving the stomach. "POU6F1 and lncRNA-CASC2, through FMRP, regulate the SOCS2/SLC7A11 signaling axis to modulate ferroptosis in gastric cancer, suggesting a novel mechanism for controlling cancer stem-like cell survival and potentially targeting cancer stemness in this disease." (PMID 40271197, 2025). "HEK293T-derived exosomes that have been loaded with circ DIDO1 (Exo-circ DIDO1) via transfection suppress the progression of gastric cancer by decreasing the expression of miR-1307-3p but increasing the expression of suppressor of cytokine signaling 2 (SOCS2)." (PMID 37242707, 2023). "In the current study, we are the first to identify miR-877-3p with upregulation in the chemo survived gastric cancer cells, which was mediated by GM-CSF induction but in turn suppressed SOCS2 and activated Jak/Stat3 signaling." (PMID 35600882, 2022). "By suppressing SOCS2 (suppressor of cytokine signaling 2), miR-101 inhibits Helicobacter pylori–induced gastric cancer tumorigenesis and tumor growth." (PMID 32318335, 2020). "Furthermore, POU6F1 was found to upregulate lncRNA CASC2, leading to reduced GSH levels through increased SOCS2-mediated ubiquitination and degradation of SLC7A11, thereby inducing ferroptosis in gastric cancer (GC) cells." (PMID 40403492, 2025).
colon carcinoma (11 papers, 2018 to 2023). "SOCS2 overexpression was detected in a murine model of azoxymethane/dextran sulfate sodium-induced colitis-associated colon cancer compared to mock-treated controls." (PMID 29622769, 2018). "SOCS2 expression causes tumor growth and progression, which could determine colon cancer prognosis." (PMID 29622769, 2018). "A higher METTL3 level can promote colon cancer cell tumorgenicity by reducing suppressor of cytokine signaling 2 (SOCS2) expression in cancer cell lines." (PMID 34363020, 2021). "SOCS2 expression was examined in murine colon cancer tissues derived from AOM/DSS-induced CAC samples." (PMID 29622769, 2018). "Moderate levels of SOCS-2 can suppress growth in colon cancer cells, but Kim’s team showed that excessive SOCS-2 has the opposite effect, promoting proliferation." (PMID 29622769, 2018). "Third, SOCS2 knockdown substantially decreased cell growth and tumorigenicity of colon cancer cell lines." (PMID 29622769, 2018). "In concordance with cell expression profiles, our experiments indicated the potential growth-promoting activity of SOCS2 in colon cancer." (PMID 29622769, 2018). "Case-control studies, using more than 1550 patients with colon cancer and 750 cases of rectal cancer, demonstrated that JAK2, SOCS2, STAT1, STAT3, STAT5A, STAT5B, and STAT6 were associated with colon cancer, and that STAT3, STAT4, STAT6, and TYK2 were linked to rectal cancer." (PMID 36982677, 2023). "Moreover, SOCS2 promoted proliferation, anchorage-independent growth, apoptosis resistance, and in vivo tumor growth of prostate and colon cancer cell lines [42−44], testifying to its oncogenic potential." (PMID 34029637, 2021). "Overexpression of SOCS2 inhibited the proliferation of Caco-2 colon cancer cell line." (PMID 33414813, 2020). "Furthermore, strong immunoreactivity for SOCS2 antigen was observed in colon carcinomas induced by azoxymethane and dextran sulfate sodium." (PMID 29622769, 2018). "SOCS2 expression was heterogeneously upregulated in some human colon cancers." (PMID 29622769, 2018). "In human colon cancer tissues, SOCS2 immunoreactivity was heterogeneously detected." (PMID 29622769, 2018). "However, most colon cancer samples showed upregulated SOCS2 expression (n = 40, P < 0.01)." (PMID 29622769, 2018). "However, varying expression of SOCS2 was seen in human colon cancer tissues." (PMID 29622769, 2018). "The current study aimed to investigate the effect of valproic acid (VPA) on SOCS-1, SOCS-2, SOCS-3, SOCS-5, SOCS6, and SOCS-7 gene expression and cell growth inhibition in colon carcinoma IS1, IS2, and IS3 cell lines." (PMID 35611249, 2022). "The results of the current study demonstrate that VPA plays its role through the upregulation of SOCS-1, SOCS-2, SOCS-3, SOCS-5, SOCS6, and SOCS-7 genes, resulting in cell growth inhibition and apoptosis induction in colon carcinoma IS1, IS2, and IS3 cell lines." (PMID 35611249, 2022).
Hepatic steatosis (10 papers, 2013 to 2024). Steatosis is a term used to denote lipid accumulation within hepatocytes. "The SOCS2 knockout mice showed an increase of 77.6% in hepatic triglycerides, whereas the hepatic steatosis caused by HFD was depressed." (PMID 33519913, 2020). "Recent reports indicate that deficiency of Socs2 in mice prevents hepatic steatosis with high fat diet, while it worsens insulin resistance, supporting metabolic roles for Socs2." (PMID 24892698, 2014). "Previous studies have found that hepatic SOCS2 deletion protects against hepatic steatosis but worsens insulin resistance in high-fat-diet-fed mice." (PMID 34803490, 2021). "Previous studies have found that hepatic SOCS2 deletion protected against hepatic steatosis but worsened insulin resistance in high-fat-diet-fed mice." (PMID 34803490, 2021). "The previous study shown SOCS2 aggravates hepatic steatosis via GH singaling pathway, however, our study found SOCS2 in marcophages limits apoptosis and inflammation." (PMID 34803490, 2021). "A high inflammatory state in SOCS2-depleted tissues was earlier documented in a hepatic steatosis model, which showed increased expression of inflammatory cytokines and enhanced NF-kB activation." (PMID 32349250, 2020). "Note, SOCS2 deletion was shown to protect against hepatic steatosis but worsens insulin resistance in high-fat-diet-fed mice while ablation of SOCS3 enhances hepatic insulin sensitivity but increases lipogenesis resulting in fatty liver and obesity." (PMID 30547786, 2018). "However, we have recently shown that deletion of SOCS2 protects against hepatic steatosis but worsen insulin resistance in high-fat diet-fed mice." (PMID 23761784, 2013). "In contrast, the ablation of SOCS2 in mice, which increases STAT5 signaling, protects from high-fat diet-induced liver steatosis." (PMID 23761784, 2013). "It has been clarified that SOCS2 participated in NAFLD and hepatic steatosis." (PMID 33228663, 2020). "The fact that we did not observe hepatic steatosis in SDNme7−/− rats could be explained by opposing actions of decreased Nrep favoring lipid deposition and downregulation of Socs2 and Pparg, both of which were shown to prevent hepatic steatosis in spite of negatively affecting insulin resistance." (PMID 33916973, 2021).
chronic myeloid leukemia (9 papers, 2012 to 2023). "SOCS2, suppressor of cytokine signaling-2, is highly upregulated and has tumor-promoting functions in the advanced stage of chronic myeloid leukemia and in high-grade anal intraepithelial lesions." (PMID 35186733, 2022). "SOCS2 expression was significantly increased in patients with chronic myeloid leukemia (CML) in blast crisis as compared with chronic phase patients and healthy controls." (PMID 34029637, 2021). "In contrast, SOCS2 is a pro-oncogene in advanced stages of chronic myeloid leukemia and in precursors of anal cancer, where it is significantly upregulated." (PMID 29622769, 2018). "Moreover, our analysis revealed that SOCS2 levels are significantly increased in patients with acute and chronic myeloid leukemia, two hematological malignancies where disease progression is closely linked to IL-1β." (PMID 31775389, 2019). "These specific effects of SOCS2 in the context of IL-1β are important because IL-1β-signaling is known to be associated with tumor progression in certain myeloid disorders such as acute myeloid leukemia (AML) and chronic myeloid leukemia (CML)." (PMID 31775389, 2019). "However, SOCS2 is highly upregulated and has tumor-promoting functions in the advanced stages of chronic myeloid leukemia and in high-grade anal intraepithelial lesions." (PMID 29622769, 2018). "Overexpression of others genes included in our signature, MSI2 (Musashi 2) and SOCS2 (Suppressor of cytokines signaling 2), predicted unfavorable outcome in AML and chronic myeloid leukemia (CML)." (PMID 22910040, 2012). "In contrast, in bone marrow cells from chronic myeloid leukaemia (CML) patients, SOCS2 is highly expressed and is thus hypothesised to be involved in advanced stages of CML21." (PMID 29559623, 2018).
glioma (9 papers, 2020 to 2024). A benign or malignant brain and spinal cord tumor that arises from glial cells (astrocytes, oligodendrocytes, ependymal cells). "The forest plot shows that EPB41L4A.AS1, GDNF.AS1, HAR1A, LINC00237, SLC25A21.AS1, SNA13.AS1, and WDFY3.AS2 are the protective factors with HR < 1, while LINC00092, LINC00265, LINC00339, LINC00665, PAXIP1.AS2, SNHG16, SNHG9 and SOCS2.AS1 are risk factors with HR>1 in glioma patients." (PMID 35273128, 2022). "In vivo and in vitro, 1C-containing Jumonji domains promote M1 macrophage polarization and inhibit the development of glioma xenografts via the miR-302a/METTL3/SOCS2 axis." (PMID 38523627, 2024). "METTL3 also exerts a similar function in glioma to inhibit M1 polarization by promoting m6A methylation of suppressor of cytokine signaling 2 (SOCS2) and reducing its expression, which is a negative regulator of the JAK/STAT pathway." (PMID 38322265, 2024). "The mRNA level of SOCS2 in clinical samples detected by RT‐qPCR exhibited an ascending trend in glioma tissues." (PMID 34586733, 2021). "In conclusion, JMJD1C promotes M1 macrophage polarization and inhibits glioma development through the miR‐302a/METTL3/SOCS2 axis." (PMID 34586733, 2021). "JMJD1C promoted M1 macrophage polarization and suppressed the growth of glioma xenografts through the miR‐302a/METTL3/SOCS2 axis both in vivo and in vitro." (PMID 34586733, 2021). "Additionally, METTL3 promotes the suppressor of cytokine signaling 2 (SOCS2) degradation in gliomas by promoting an m6A methylation modification of SOCS2 to inhibit M1 macrophage polarization." (PMID 37759870, 2023). "The protein expression of SOCS2 was also increased in glioma tissues." (PMID 34586733, 2021). "Also, methyltransferase‐like 3 (METTL3) has been found to be upregulated in the tumorigenic glioma stem‐like cells, while suppressor of cytokine signaling 2 (SOCS2) exerts inhibitory effects on glioma." (PMID 34586733, 2021). "In view of the importance of SOCS2 in modulating macrophage polarization, we propose that targeting SOCS2 may represent an innovative approache to treat glioma." (PMID 34586733, 2021). "Furthermore, we investigated the effect of mRNA methylase METTL3 on SOCS2 expression in glioma cells." (PMID 34586733, 2021). "The increase in SOCS2 expression promotes the M1 TAM population in glioma tumors, resulting in the suppression of glioma growth." (PMID 37345170, 2023). "Co-culture of monocyte and glioma cells demonstrated that glioma cells overexpressing METTL3 inhibited SOCS2 expression and M1 polarization of monocytes, while SOCS2 overexpression could rescue this inhibition." (PMID 37671161, 2023). "However, the current study provides evidence that JMJD1C plays a tumor‐inhibiting role in glioma by upregulating miR‐302a and further affecting the METTL3/SOCS2‐mediated polarization of M1 macrophages." (PMID 34586733, 2021).
melanoma (9 papers, 2017 to 2024). A malignant, usually aggressive tumor composed of atypical, neoplastic melanocytes. "In addition, SOCS2 has also been identified to play a role in other cancer types such as melanoma, where specific loss of SOCS2 in DCs enhanced anti-tumoral immunity in a melanoma mouse model." (PMID 31775389, 2019). "Previous studies have also shown that Socs2 expression is upregulated by IFN-γ in DCs in human melanoma." (PMID 39185412, 2024). "In the immune system, SOCS2 is an IFNγ signature gene in mononuclear phagocytes infiltrating primary human melanoma, and in mouse models acts to limit adaptive anti-tumoral immunity and DC-based priming of T cells." (PMID 34857742, 2021). "In addition, constitutive IFN-γ signaling in metastatic human melanomas has been associated with an upregulation of the protein suppressor of cytokine signaling-2 (SOCS2) in DCs, which limits their ability to prime T cells, and may serve as a marker of “exhausted” regulatory DCs." (PMID 31921140, 2019). "In addition, Socs2 is upregulated by interferon-gamma (IFNγ) in DCs in human melanoma, and Socs2−/− mice exhibit enhanced DC priming of Tcell responses to give improved antitumor immunity." (PMID 34857742, 2021). "To investigate whether loss of SOCS2 affects NK cell-mediated anti-tumor activity in vivo, we challenged WT and SOCS2−/− mice with B16F10 melanoma cells." (PMID 28383049, 2017). "Furthermore, SOCS2−/− mice showed a reduction in lung metastases and an increase in survival following melanoma challenge." (PMID 28383049, 2017).
colorectal cancer (8 papers, 2017 to 2026). A primary or metastatic malignant neoplasm that affects the colon or rectum. "In colorectal cancer, SOCS2 inhibits Caco-2 cell proliferation and promotes cell differentiation." (PMID 38071211, 2023). "Low levels of SOCS2 contribute to the maintenance of leucine-rich repeat-containing G-protein coupled receptor 5 expression, a critical factor for the continuous self-renewal of intestinal epithelial cells and a recognized marker of cancer stem cells in colorectal cancer." (PMID 41517663, 2026). "The role of m6A methyltransferases in tumors has been partially reported; for example, METTL3 upregulation promotes the malignant progression of HCC by inhibiting SOCS2 expression through an m6A-dependent mechanism, and METTL14 inhibits proliferation and metastasis in colorectal cancer." (PMID 35494016, 2022). "In colorectal cancer (CRC), SOCS2 is also considered favorable for clinical outcome." (PMID 33758600, 2021).
liver fibrosis (8 papers, 2020 to 2024). "LncRNA NEAT1/microRNA-129-5p/SOCS2 axis regulates liver fibrosis in alcoholic steatohepatitis." (PMID 39133718, 2024). "This indicates that the high expression of CIT can mediate the fibrosis progression of NASH, thereby leading to the occurrence and development of HCC, and TEAD4 and SOCS2 may affect HCC through pathways other than liver fibrosis." (PMID 38102321, 2023). "Additionally, we have evidenced that the suppressed NEAT1 and SOCS2, and the promoted miR-129-5p were able to attenuate the liver fibrosis in ASH mice." (PMID 33228663, 2020). "It is also important to note that inhibition of lncRNA NEAT1 inhibits the development of liver fibrosis and ASH by elevating miR-129-5p and inhibiting SOCS2." (PMID 34899344, 2021). "This miR may suppress liver fibrosis by directly regulating the non-coding RNA long nuclear paraspeckle assembly transcript 1 (NEAT1) and suppressor of cytokine signaling 2 (SOCS2)." (PMID 38067261, 2023). "We have found that the inhibited NEAT1 could suppress liver fibrosis in ASH mice by promoting miR-129-5p and restraining SOCS2, thereby decelerating the development of ASH." (PMID 33228663, 2020). "Our research aimed to assess the role of the NEAT1/miR-129-5p/SOCS2 axis in ASH development, and we have discovered that the inhibited NEAT1 could repress liver fibrosis and development of ASH through the elevation of miR-129-5p and suppression of SOCS2." (PMID 33228663, 2020). "This study was designed to elucidate the role of the NEAT1/miR-129-5p/SOCS2 axis in the progression of ASH, and we inferred that the inhibited NEAT1 may repress liver fibrosis in ASH mice by regulating miR-129-5p and SOCS2." (PMID 33228663, 2020).